ERBB4 (erb-b2 receptor tyrosine kinase 4)
Diseases named in the same sentence as ERBB4 in open-access papers (continued):
Sharing a sentence is not in itself a finding about the gene and the disease.
schizophrenia (continued). "ErbB1 as well as ErbB4 is distributed in all the cell populations that are implicated in schizophrenia neuropathology, including GABAergic neurons, dopaminergic neurons, and glial cells." (PMID 23408472, 2013). "The first 3-SNP haplotype of ERBB4 (rs707284-rs839523-rs7598440), surrounding exon 3, was found to be previously associated with schizophrenia in the Ashkenazi population." (PMID 23301017, 2013). "Recent association studies have revealed genomic regions of NRG1 and ERBB4, which are significantly associated with risk of developing schizophrenia; however, inconsistencies exist in terms of validation of findings between distinct populations." (PMID 23301017, 2013). "An earlier study has shown that mice heterozygous for ERBB4 are associated with behavioural phenotypes of schizophrenia." (PMID 23301017, 2013). "Genetic studies have also demonstrated that schizophrenia is associated not only with the ligand NRG but also with its receptor ErbB4." (PMID 23408472, 2013). "Here, we have identified a novel 6-kb haplotype block in ERBB4 on chr2 between the positions, 212,156,823 and 212,162,848, which was significantly associated with risk of developing schizophrenia in the Caucasian samples of CATIE and GAIN datasets." (PMID 23301017, 2013). "The first 3-SNP haplotype (rs707284-rs839523-rs7598440) surrounding exon 3 of ERBB4 was found to be significantly associated with schizophrenia in Ashkenazi Jewish population." (PMID 23301017, 2013). "Schizophrenia patients who carried 3 NRG1/ERBB4/AKT risk genotypes were disproportionately worse in dorsolateral prefrontal function in the image study." (PMID 22558359, 2012). "This interpretation is functionally consistent with the genetic association of NRG1 and ERBB4 with schizophrenia." (PMID 22087295, 2011). "Selective loss of ErbB4 in PV cells causes a disinhibition of prefrontal pyramidal cells and results in a schizophrenia-like phenotype in mice." (PMID 21876820, 2011). "Single nucleotide polymorphisms (SNPs) in the genes encoding Neuregulin-1 (NRG1) and its receptor ErbB4 are associated with increased risk for and endophenotypes of schizophrenia; NRG1 is also associated with bipolar disorder." (PMID 22087295, 2011). "In this study, we investigatethe role of rare coding variants in ERBB4 in BP cases withmood-incongruent psychotic features, a form of BP with arguably the greatestphenotypic overlap with schizophrenia." (PMID 21637803, 2011). "Genetic variation in ErbB4 is associated with schizophrenia and risk-associated polymorphisms predict overexpression of ErbB4 CYT-1 isoforms in the brain in the disorder." (PMID 20886074, 2010). "Linkage and association analyses have identified neuregulin 1 and its receptor ErbB4 as susceptibility genes for schizophrenia and recently partial deletions of the ErbB4 gene have been reported in the disorder." (PMID 20886074, 2010). "Nonetheless, several recent publications report an association between schizophrenia and ErbB4, one of the receptors for NRG1." (PMID 17598910, 2007). "Although the associations of erb-b2 receptor tyrosine kinase 4 (ErbB4) with various neuropsychiatric diseases, including schizophrenia and bipolar disorder, have been widely examined, the physiological roles of ErbB4 in PTSD and fear responses remain unclear." (PMID 39623093, 2024). "This study underscores the role and regulation of nNOS within a specific subset of GABAergic interneurons, offering insights into the pathophysiological mechanisms of schizophrenia, given the association of Nrg1, Erbb4, Pi3k, and Nos1 genes with this mental disorder." (PMID 38396027, 2024). "Fifteen ErbB4 sequence variants have been associated with schizophrenia." (PMID 36119496, 2022). "NRG1/ErbB4 signaling is strongly linked to working memory dysfunction, and several recent studies have investigated its relevance as a candidate therapeutic pathway for schizophrenia." (PMID 35876932, 2022).
schizophrenia (continued). "Importantly, genetic variants of NRG1–NRG3 and ErbB4 are associated with an increased risk for schizophrenia and its endophenotypes." (PMID 36012727, 2022). "From these findings, dysfunction of NRG-1/erbB4 signaling may be associated with development of schizophrenia." (PMID 36620856, 2022). "Moreover, mutant mice carrying mutations in the NRG-1 or erbB4 gene show schizophrenia-like behaviors such as disruption of PPI, latent inhibition and cognitive deficits." (PMID 36620856, 2022). "NRG1 and its receptor ErbB4 have been linked to abnormal cortical function in schizophrenia." (PMID 36460658, 2022). "Interestingly, Zswim6 is expressed in the medial habenula in which the schizophrenia-risk gene ErbB4 is also highly expressed." (PMID 34054439, 2021). "Mutations in the ErbB4 gene have been linked with schizophrenia." (PMID 34393751, 2021). "Finally, substantial evidence associate Nrg/Erbb4 signaling to neurodevelopmental disorders such as schizophrenia." (PMID 34957103, 2021). "We also show that ErbB4 KO mice reproduce several behavioral deficits associated with altered striatal, hippocampal and/or cortical function that are relevant to psychiatric disorders, including schizophrenia." (PMID 32354758, 2020). "Interestingly, we previously found that NRG1/ErbB4 (susceptibility genes of schizophrenia) signaling is critical for EAAC1 expression and function." (PMID 32818073, 2020). "Previously, it has been reported that ErbB4 is a schizophrenia susceptibility gene." (PMID 32117963, 2020). "Moreover, the main receptor for NRG1 signaling, ErbB4, itself a schizophrenia risk gene (Schizophrenia Working Group of the Psychiatric Genomics Consortium, 2014), is expressed in PV+ and CCK+ GABAergic interneurons but not in glutamatergic pyramidal cells." (PMID 29740596, 2018). "Using association analysis method, one study showed variants in NRG1 (rs2919381) and ERBB4 might contribute to susceptibility to schizophrenia in Japanese population." (PMID 28993723, 2017). "According to these Nrg1 genetic models, it is possible that dysfunction of NRG1 or NRG1/ErbB4 signaling may affect neural development and synaptic plasticity by disturbance of glutamatergic or GABAergic systems implicated in schizophrenia." (PMID 28993723, 2017). "Additionally, evidence suggests that PI3K signaling is impaired in the brains of patients with schizophrenia and its impairment is closely related to schizophrenia-associated genetic variants in ErbB4, the NRG-1 receptor." (PMID 27057274, 2016). "I have used the ErbB4-/- HER4heart KO mice to study the neurodevelopmental insults associated to deficiencies in the NRG1-ErbB4 signaling pathway and their potential implication with brain disorders such as schizophrenia, a chronic psychiatric disease affecting 1% of the population worldwide." (PMID 26733804, 2015). "A receptor of NRG1, ERBB4 is also associated with schizophrenia." (PMID 25805966, 2015). "Both ErbB4, as well as Nrg-1 have been identified as risk genes for schizophrenia." (PMID 24592210, 2014). "Along these lines, many groups have reported association of the NRG1 – ERBB4 risk variants with neurocognitive, electrophysiological and neuroimaging schizophrenia-related outcome variables, including altered fronto-temporal brain function and white matter density and integrity." (PMID 24478629, 2014). "The variety of functions subserved by NRG in the brain's development suggests the possibility that other SNP or haplotypes related to NRG1 and/or ERBB4 may be associated to cognitive deficit and/or disorganized cortical activity in schizophrenia." (PMID 24976857, 2014). "Interestingly, kalirin-7, NRG1, and ErbB4 are highly and specifically expressed in GABAergic interneurons, and have been associated with schizophrenia." (PMID 25309333, 2014).
schizophrenia (continued). "It has previously been reported that three intronic risk SNPs (rs7598440, rs707284, rs839523) which comprise a core-risk haplotype are associated with increased genetic risk for schizophrenia and augmented expression of a family of ErbB4 CYT-1 transcripts in the brain of patients with the disorder." (PMID 20886074, 2010). "In addition to providing further evidence of NRG1 and ERBB4 associations to schizophrenia, our study is the first to suggest possible involvement of three additional genes from the NRG and ERBB gene families, i.e. NRG2, NRG3 and EGFR (ERBB1)." (PMID 17598910, 2007). "The interactions within the ERBB4 gene suggest that combinations of particular genotypes may result in modified receptor activity, leading to altered risk of schizophrenia." (PMID 17598910, 2007). "Furthermore, several recent reports suggest association between schizophrenia and single-nucleotide polymorphisms (SNPs) in ERBB4, one of the receptors for Neuregulin-1." (PMID 17598910, 2007). "Furthermore, overactive ERBB4 is associated with reduced interneuron activity in the prefrontal cortex leading to an imbalance of excitation and inhibition, and consecutively to symptoms of schizophrenia." (PMID 38303712, 2024). "However, the mutation of genes NRG1 or ErbB4 may only account for a small part of schizophrenia cases." (PMID 33897409, 2021). "Importantly, numerous independent studies have identified a genetic association of natural variants of NRG1, NRG3, and ErbB4 with schizophrenia, as well as with altered electrophysiological properties of inducible pluripotential stem cells isolated from schizophrenia patients." (PMID 32354758, 2020). "Neuregulin 3 (NRG3), a specific ligand for ErbB4 and a neuronal-enriched neurotrophin is implicated in the genetic predisposition to a broad spectrum of neurodevelopmental, neurocognitive and neuropsychiatric disorders, including Alzheimer's disease, autism and schizophrenia." (PMID 25093331, 2014). "A larger Scottish study has shown that 14 out of 109 SNPs in the ERBB4, mostly located at the two ends of the gene, are significantly associated with schizophrenia according to both allelic and genotypic genetic models, but a consistent pattern could not be observed." (PMID 23301017, 2013). "Two recent studies have shown that both the CYT-1 isoform and JM-a isoform are overexpressed in the dorsolateral frontal cortex of schizophrenic patients and suggest that dysregulated splice variant expression of Erbb4 may underlie the genetic association of Erbb4 with schizophrenia." (PMID 17880691, 2007). "In conclusion, this study explored the association of the ERBB4 rs839523C/T and GABRB2 rs1816072 T/C polymorphisms with schizophrenia risk in the Lebanese population." (PMID 40977746, 2025). "For example, guidance receptors such as Robo1/2 and ErBb4 have been linked to neurodevelopmental disorders, such as Autism Spectrum Disorder for Robo1/2 and schizophrenia and bipolar disorder for ErbB4." (PMID 40661145, 2025). "Considering the physiological actions that ErbB4 performs in the development and maintenance of inhibitory synapses, its well-established correlation with neuropsychiatric disorders, such as schizophrenia and bipolar disorder, is noteworthy." (PMID 39623093, 2024). "Dysregulated alternative splicing of ERBB4 has also been reported in the cerebral cortex of schizophrenia patients." (PMID 38490084, 2024). "This further underscores the relevance of nNos deletion in Erbb4-positive neurons to schizophrenia-like behaviors and highlights the potential therapeutic effects of clozapine in mitigating these deficits." (PMID 38396027, 2024). "In the open-field test, Erbb4-nNos−/− mice displayed an increased total distance traveled compared to controls, suggesting a schizophrenia-like locomotor hyperactivity phenotype." (PMID 38396027, 2024).
schizophrenia (continued). "Recently, molecular alterations in ERBB4/HER4 receptor (loss-of-function) or in NRG1 have been linked to several neurological diseases such as amyotrophic lateral sclerosis (ALS) and schizophrenia." (PMID 38369520, 2024). "Intriguingly, the genetic deletion of nNos from Erbb4-positive neurons induces schizophrenia-relevant behavioral deficits, including hyperactivity, impaired sensorimotor gating, and deficient working memory and social interaction." (PMID 38396027, 2024). "Recently, molecular alterations in ERBB4/HER4/ALS19 receptors (loss of function) have been linked to several neurological diseases such as ALS and schizophrenia." (PMID 38369520, 2024). "A mutant mouse model, where ErbB4 was specifically knocked out in PV+ interneurons (PV-Cre;ErbB4−/−), demonstrated a schizophrenia-like phenotype." (PMID 38563502, 2024). "The interaction between NRG1 and ErbB4 is believed to play a role in the pathological mechanisms of schizophrenia." (PMID 38433839, 2024). "The intracellular kinase domain deletion of Erbb4 has been found in schizophrenia patients, and molecular pathway analysis of structural variants strongly implicates NO signaling in schizophrenia." (PMID 38396027, 2024). "ErbB4 is involved in regulating various neuropsychiatric disorders, including schizophrenia, anxiety, and seizures; this receptor is mainly expressed in the PVN of hypothalamus." (PMID 36175956, 2022). "Two other schizophrenia susceptibility genes are NRG1 and ERBB4, which are part of the “signaling by ERBB4” and “long-term potentiation” pathway together with DLG4." (PMID 36561312, 2022). "Neuregulin 1 (NRG1) and its receptor ErbB4 are susceptibility genes of schizophrenia, and endogenous NRG1-ErbB4 signaling is critical to maintaining GABAergic activity, especially in PVIs." (PMID 36359279, 2022). "Although an extensive coverage of the literature in this field is beyond the scope of this review, we will briefly summarize some of the research addressing the role of ErbB4 in schizophrenia, Alzheimer’s disease (AD), and Parkinson’s disease (PD)." (PMID 36119496, 2022). "Recently, the NRG1/ErbB4 signaling pathway emerged as a candidate therapeutic target for schizophrenia." (PMID 35876932, 2022). "Previous studies have pointed out the role of NRG1 and its receptor ErbB4 in the pathophysiology of schizophrenia." (PMID 35876932, 2022). "Aberrant alternative splicing has been reported in SZ in several genes related to neurodevelopment and neurological function, including DISC1 (disrupted in schizophrenia 1) and ErbB4 (Erb-B2 receptor tyrosine kinase 4)." (PMID 36226104, 2022). "NRG-1 or erbB4 knock out mice exhibit schizophrenia-like behaviors such as disruption of PPI, latent inhibition and cognitive deficits." (PMID 36620856, 2022). "Genes and proteins that have been linked to the regulation of spine morphology and development, such as Neuregulin-1 and ErbB4 or Cdc42, show aberrant expression or signaling in schizophrenia patients." (PMID 35496908, 2022). "GOMAFU also regulates the expressions of DISC1 (disrupted in schizophrenia 1) and ERBB4 (Erb-B2 receptor tyrosine kinase 4) genes." (PMID 36010595, 2022). "Both NRG1 and ErbB4 are risk genes for brain disorders including major depressive disorder (MDD) and schizophrenia (SZ)." (PMID 33854034, 2021). "Mutant mice heterozygous for either Nrg1 or its receptor, Erbb4, show a behavioral phenotype that overlaps with mouse models for schizophrenia." (PMID 34072341, 2021). "ErbB4 null mice and those with conditional deletion of ErbB4 from hippocampal fast-spiking PV interneurons exhibited a schizophrenia-like phenotype and had several synaptic deficits." (PMID 34393751, 2021). "Studies suggest that NRG1/ErbB4 interactions play a vital role in the pathological mechanism of schizophrenia." (PMID 33897409, 2021).
schizophrenia (continued). "Other genes in this FOXP2 gene cluster include NRG3, ERBB4, DLX1, ROBO2, and ROBO2, all are susceptibility gene in schizophrenia and is related to development." (PMID 33658499, 2021). "Our findings indicate that ErbB4 signaling affects tonic DA levels and modulates a wide array of behavioral deficits relevant to psychiatric disorders, including schizophrenia." (PMID 32354758, 2020). "In relation to schizophrenia, there are contrasting reports regarding the effects of ERBB4 expression levels." (PMID 32531902, 2020). "Neural trophic factor neuregulin 1 (NRG1) and its receptor ErbB4 are two schizophrenia-related genes." (PMID 32117963, 2020). "For instance, genes casually linked to schizophrenia such as Disrupted in schizophrenia-1 (DISC1), Reelin, neuroregulin (NRG), and its receptor, ERBB4, control neuronal migration during brain development." (PMID 30112632, 2019). "Recent work showed that deletion of a schizophrenia-related gene, ErbB4 from TRN-SOM neurons impairs sensory selection." (PMID 30837664, 2019). "In parvalbumin-positive (PV) interneurons, ErbB4 is involved in the etiology of schizophrenia and epilepsy." (PMID 30179154, 2018). "Erbb4 is a genetic susceptibility gene for schizophrenia, with many studies reporting the crucial role of ErbB4 in the pathogenesis of schizophrenia." (PMID 30179154, 2018). "While genetic studies link NRG1 and its receptor ERBB4 to schizophrenia and other brain disorders, how NRG1 dysfunction impacts brain function is not fully understood." (PMID 29844389, 2018). "In SCZ patient brains, DISC1 (disrupted in schizophrenia 1), ERBB4 (v-erb-a erythroblastic leukemia viral oncogene homolog 4) and their alternatively spliced variants were all down-regulated due to MIAT up-regulation." (PMID 30728830, 2018). "While changes in Nrg1 expression levels in schizophrenia still remain controversial, understanding the BACE1-cleaved Nrg1-ntf and Nrg1/ErbB4 signaling in schizophrenia neuropathogenesis is essential and important." (PMID 28993723, 2017). "Transgenic mice overexpressing Nrg1 type III display cortical Erbb4 hyperphosphorylation, a condition observed in postmortem brains from schizophrenia patients." (PMID 28743784, 2017). "Results revealed increased TLR4/TLR5 and decreased ErbB4 expression in schizophrenia relative to the control subjects." (PMID 28646138, 2017). "Several human postmortem brain studies have shown dysregulation of gene expression of NRG1, ErbB4 or down-stream targets among individuals with schizophrenia." (PMID 29163244, 2017). "Decreased levels of NRG-1 and its receptor ErbB4 are observed in prefrontal cortex of patients with schizophrenia and the NRG-1 gene has been identified as a leading susceptibility locus for schizophrenia." (PMID 27057274, 2016). "This process involves ErbB4-TrkB interaction, which is decreased in the brain in individuals with schizophrenia." (PMID 27134685, 2016). "My results also suggest an ErbB4-dependent role in oligodendrocytes development and myelin production, which coincide with previous studies in mouse models and schizophrenia." (PMID 26733804, 2015). "The ErbB4 KO model presents a complete array of neurodevelopmental defects consistent with the prognosis and development of the schizophrenia in the adult brain." (PMID 26733804, 2015). "The ErbB4-/- HERheart mice have been extensively used in functional and behavioral studies of schizophrenia; however, a neuroanatomical characterization of the mouse model has not been analyzed in detail." (PMID 26733804, 2015). "Cell-specific gene modification techniques are now starting to elucidate a link between Nrg1/ErbB4 signaling and pathophysiology of schizophrenia." (PMID 25805966, 2015). "The susceptibility genes for schizophrenia Neuregulin-1 (NRG1) and ErbB4 have critical functions during brain development and in the adult." (PMID 26733804, 2015).